ANGPT1 (angiopoietin 1)
Diseases named in the same sentence as ANGPT1 in open-access papers (continued):
Sharing a sentence is not in itself a finding about the gene and the disease.
malignant mesothelioma (2 papers, 2020 to 2021). A malignant neoplasm of the pleura or peritoneum, arising from mesothelial cells. "Angiopoietin-1 has been proposed to be a useful prognostic marker in malignant mesothelioma with important roles in tumor growth." (PMID 33562126, 2021). "MMP-7 and angiopoietin-1 have no discriminative capacity to distinguish between malignant mesothelioma and benign effusions." (PMID 32731396, 2020).
mesothelioma (2 papers, 2021 to 2023). A usually malignant and aggressive neoplasm of the mesothelium which is often associated with exposure to asbestos. "In addition, mesothelioma patients have shown higher serum levels of angiopoietin-1 compared to patients with benign conditions." (PMID 33562126, 2021). "In mesothelioma cells, among the angiogenesis-related proteins, angiopoietin-1, thrombospondin-1 (TSP-1), and tissue inhibitor of metalloproteinases-1 (TIMP-1) were significantly downregulated upon SDC-1 over-expression, whereas IL-8 was upregulated upon SDC-1 silencing." (PMID 33562126, 2021).
non-small cell lung carcinoma (2 papers, 2021 to 2024). A group of at least three distinct histological types of lung cancer, including non-small cell squamous cell carcinoma, adenocarcinoma, and large cell carcinoma. "With regard to down-regulated genes involved in angiogenesis within the canonical HIF-1 signaling pathway, angiopoietin 1 (ANGPT1)—a putatively favorable serum prognostic marker for non-small cell lung cancer —had suppressed expression across LUAD tumor at stages 1–4." (PMID 34940617, 2021). "However, clinical studies have demonstrated downregulation of ANGPT1 and TEK expression levels in non-small-cell lung cancer (NSCLC) tissue." (PMID 39595659, 2024).
oral squamous cell carcinoma (2 papers, 2019 to 2020). "Experimental study recently demonstrated that an in vitro treatment with angiopoietin-1 for Tie2-overexpressed oral squamous cell carcinoma cells enhances the cell-cell and cell-extracellular matrix adhesive activities of cancer cells." (PMID 32799882, 2020). "The study has shown that compared with the healthy oral mucosa, angiopoietin-2 is overexpressed and angiopoietin-1 is downregulated in tumor samples of oral squamous cell carcinoma." (PMID 32799882, 2020). "Previous studies have shown downregulation of ANGPT1 in 80–95 % of oral squamous cell carcinomas." (PMID 31461552, 2019).
ovarian carcinoma (2 papers, 2020 to 2021). A malignant neoplasm originating from the surface ovarian epithelium. "The upregulation of ANGPT found in our RNASeq analysis is consistent with studies using mouse models wherein an increased expression of angiopoietins (ANGPT1, ANGPT2, and ANGPT4 and TIE2 (angiopoietin receptor) have been shown to promote ovarian cancer progression." (PMID 35052372, 2021).
papillary thyroid cancer (2 papers, 2013 to 2022). "Recent research indicated that Angiopoietin-1 played a role in lymph node metastasis and invasiveness of papillary thyroid carcinoma TIMPs, which comprise a family of four protease inhibitors: TIMP1, TIMP2, TIMP3, and TIMP4." (PMID 36672532, 2022).
Parkinson disease (2 papers, 2021 to 2023). A progressive degenerative disorder of the central nervous system characterized by loss of dopamine producing neurons in the substantia nigra and the presence of Lewy bodies in the substantia nigra and locus coeruleus. "Moreover, C16 has shown a beneficial effect on the ALS/Parkinsonism dementia complex (PDC), representing symptoms analogous to AD’s such as dementia and Parkinsonism, when administrated along with angiopoietin 1, a nerve growth factor." (PMID 36671492, 2023).
pituitary tumor (2 papers, 2016 to 2022). A benign or malignant neoplasm affecting the pituitary gland. "Compared with normal pituitary tissue, the overall expression of ANGPT1 was significantly lower in pituitary tumor tissue by 2.1-fold (p=0.0043)." (PMID 35600354, 2022). "The overall expression of ANGPT1 was 5.4 x 103 copies/μg total RNA in pituitary tumor tissue." (PMID 35600354, 2022). "Elevated SPP1, COL1A1 and NT5E proteins may be secreted from the pituitary tumor to directly target the skeletal system, with resultant osteoporosis, while downregulated HTRA1 and ANGPT1 may deregulate in bone formation and development." (PMID 27690016, 2016).
pneumonia (2 papers, 2022 to 2023). An acute, acute and chronic, or chronic inflammation focally or diffusely affecting the lung parenchyma, caused by an infection in one or both of the lungs (by bacteria, viruses, fungi, or mycoplasma.). "The levels of IL-6, procalcitonin, sRAGE, and angiopoietin-2 were lower post-event compared to the day of pneumonia diagnosis, while syndecan-1 and angiopoietin-1 concentrations were higher post-event; the other host response biomarkers remained unaltered." (PMID 37415223, 2023).
proliferative diabetic retinopathy (2 papers, 2023 to 2024). Advanced retinopathy due to diabetes mellitus characterized by the formation of new vessels in the retina. "We detected up-regulated levels of VEGF-A (p = 0.001), PIGF (p<0.001), Angiopoietin-1 (p = 0.005), Angiopoietin-2 (p<0.001), IL-1β (p = 0.012), and IL-8 (p = 0.018) in proliferative diabetic retinopathy samples." (PMID 36662891, 2023).
renal cell carcinoma (2 papers, 2014 to 2024). "The study about human renal cell carcinoma showed that elevated PDGF-D induced angiogenesis and metastasis in a mouse model, in which the expression of angiopoietin-1 and MMP9 were increased." (PMID 24646915, 2014).
renal fibrosis (2 papers, 2016 to 2018). A final common manifestation of a wide variety of chronic kidney diseases characterized by glomerulosclerosis and tubulointerstitial fibrosis. "Also, tubular cell specific overexpression of Angpt1 attenuated renal fibrosis after UUO." (PMID 29293543, 2018).
sickle cell anemia (2 papers, 2018 to 2022). "The study provides a first report on plasma levels of angiopoietin-1, angiopoietin-2, and vascular endothelial growth factors, as well as Ang-2/Ang-1 ratios, in homozygous sickle cell disease patients in Ghana." (PMID 29954157, 2018). "The study provides a first report on plasma levels of angiopoietin-1, angiopoietin-2, and vascular endothelial growth factors in homozygous sickle cell disease patients in Ghana." (PMID 29954157, 2018).
triple-negative breast carcinoma (2 papers, 2023 to 2024). An invasive breast carcinoma which is negative for expression of estrogen receptor (ER), progesterone receptor (PR), and human epidermal growth factor receptor 2 (HER2). "A clinical sample database showed that ANGPT1 promoted the proliferation of triple-negative breast cancer cells." (PMID 39302921, 2024).
type 1 diabetes (2 papers, 2018 to 2022). "Podocyte specific repletion of angiopoietin-1 in a model of type 1 diabetes decreased glomerular endothelial cell proliferation, hyperfiltration and albuminuria by 70%." (PMID 29783932, 2018). "Angiopoietin 1 (Ang1) is known to restore eGlx and so was used to investigate whether eGlx restoration reverses diastolic dysfunction in mice with type 1 diabetes." (PMID 35211778, 2022).
Ureteral obstruction (2 papers, 2018). Obstruction of the flow of urine through the ureter. "Inducible Angpt1 knockout mice were subjected to unilateral ureteral obstruction (UUO) to induce fibrosis, and kidneys were collected at different time points up to 10 days after obstruction." (PMID 29293543, 2018).
acute myeloid leukaemia (1 paper, 2018). "In acute myeloid leukaemia, the FAK pathway regulates the expression of a number of cytokines (interleukin 6 (IL 6), IL 8, stromal cell-derived factor 1, and angiopoietin 1), which are crucial for CSCs maintenance." (PMID 29568377, 2018).
adenomyosis (1 paper, 2025). The growth of endometrial tissue inside the muscular wall of the uterine corpus. "Our study demonstrates that LNG-IUS treatment is associated with lower protein expression of VEGF, ANGPT-1, and ANGPT-2 in adenomyosis, with levels approaching those observed in normal controls." (PMID 41464535, 2025). "The LNG-IUS attenuates ANGPT-1, ANGPT-2, and VEGF expression at both the protein and transcript levels, suggesting that modulation of angiogenic pathways may contribute to its therapeutic benefit in abnormal uterine bleeding associated with adenomyosis." (PMID 41464535, 2025). "The protein expression of ANGPT-1, ANGPT-2, and VEGF was significantly elevated in both eutopic and ectopic endometria of patients with adenomyosis compared with normal controls." (PMID 41464535, 2025). "In adenomyosis patients using the LNG-IUS, these expression levels were lower and approached those of the control group, ANGPT1, ANGPT2, and VEGFA mRNA in eutopic endometria showed concordant downregulation." (PMID 41464535, 2025). "We compared vascular endothelial growth factor (VEGF), angiopoietin-1 (ANGPT-1), and angiopoietin-2 (ANGPT-2) expression in eutopic and ectopic endometria from patients with adenomyosis and evaluated whether the levonorgestrel intrauterine system (LNG-IUS) modulates these angiogenic markers." (PMID 41464535, 2025). "Although TIE-2 receptor expression itself remains stable during the menstrual cycle, our observation of increased ANGPT-1 and ANGPT-2 levels in adenomyosis patients indicates that altered ligand activity, rather than receptor availability, may contribute to aberrant angiogenesis." (PMID 41464535, 2025). "The objective of this study was therefore to evaluate the expression of VEGF, ANGPT-1, and ANGPT-2 in eutopic and ectopic endometria from patients with adenomyosis—with and without LNG-IUS insertion—compared with normal controls." (PMID 41464535, 2025).
Airway obstruction (1 paper, 2016). Obstruction of conducting airways of the lung. "A positive correlation found between Angiopoietin-1 levels and airway obstruction reversibility, may reflect involvement of this factor in the modulation of a smooth muscle constriction." (PMID 26937244, 2016).
amyloid (1 paper, 2022). "Thus, the up-regulation of ANGPT1, SORCS2 and MMP2 in AD ONS cells is consistent with enhanced amyloid-associated degenerative effects." (PMID 36291125, 2022).
anemia (1 paper, 2025). A reduction in the number of red blood cells, the amount of hemoglobin, and/or the volume of packed red blood cells. "Patients with low concentrations might be prioritized for enhanced nutritional support, tighter anemia correction, or early referral to aggressive rehabilitation protocols, while those with markedly depressed ANGPT1 could be considered for adjunctive pro-angiogenic strategies." (PMID 41195181, 2025).
aneurysm (1 paper, 2023). Bulging or ballooning in an area of an artery secondary to arterial wall weakening. "This conclusion was confirmed in another study, where endothelial progenitor cells with overexpressed ANGPT-1 were proposed as a promising strategy for the treatment of aneurysm due to their strong ability to improve organization of fibrotic components in the aneurysms and enhance angiogenesis." (PMID 37569462, 2023).
angiosarcoma (1 paper, 2018). A malignant tumor arising from the endothelial cells of the blood vessels. "Phase II study of the angiopoietin 1 and 2 peptibody trebananib for the treatment of angiosarcoma." (PMID 30701027, 2018).
beta thalassemia (1 paper, 2025). Beta-thalassemia (BT) is characterized by deficiency (Beta+) or absence (Beta0) of synthesis of the beta globin chains of hemoglobin (Hb). "On the other hand, there are several reports indicating that patients with beta-thalassemia have elevated growth factors, like VEGF and angiopoietin-1, which are associated with irregular angiogenesis." (PMID 41246624, 2025).
cholangiocarcinoma (1 paper, 2025). A carcinoma that arises from the intrahepatic biliary tree (intrahepatic cholangiocarcinoma) or from the junction, or adjacent to the junction, of the right and left hepatic ducts (hilar cholangiocarcinoma). "For example, in cholangiocarcinoma, bile induces MCs to secrete platelet-derived growth factor B and angiopoietin 1/2, enhancing angiogenesis in cholangiocarcinoma." (PMID 41425713, 2025).
chronic myelogenous leukemia (1 paper, 2020). "Mouse models of chronic myelogenous leukemia (CML) showed significant reductions in the expression of HSC niche factors, including Cxcl12, Lepr, Kitl and Angpt1, and concomitant expansion of osteolineage cells." (PMID 33324418, 2020).
colorectal tumors (1 paper, 2024). "In conclusion, we identified a significant increased VEGF-A and decreased ANGPT-1 expressions in EMAST+ colorectal tumors in CRC patients." (PMID 38719941, 2024). "We identified a significantly increased VEGF-A (P-value = 0.002) and decreased ANGPT-1 (P-value = 0.04) expression in EMAST+ colorectal tumors." (PMID 38719941, 2024). "Moreover, our study identified a significant association between VEGF-A and ANGPT-2 overexpression, as well as ANGPT-1 downregulation with colorectal tumor metastasis and reduced overall survival." (PMID 38719941, 2024).
Dengue virus infection (1 paper, 2016). "Altered ratios between angiopoietin-1 and −2 impair the barrier function of the endothelial monolayer during Dengue virus infection." (PMID 27842513, 2016).
dermatitis (1 paper, 2023). An inflammatory process affecting the skin. "Other biomarkers under investigation are angiopoietin-1 (Ang-1) and CD40 ligand, whose baseline high levels have been related to dermatitis." (PMID 36900420, 2023).
dialysis (1 paper, 2024). "Our objective was to examine the factors associated with the serum angiopoietin-2/angiopoietin-1 (Angpt-2/Angpt-1) ratio in peritoneal dialysis (PD) patients and to investigate the association between Angpt-2/Angpt-1 ratio and cardiovascular and all-cause mortality." (PMID 39082686, 2024).
Duchenne muscular dystrophy (1 paper, 2025). Duchenne muscular dystrophy (DMD) is a neuromuscular disease characterized by rapidly progressive muscle weakness and wasting due to degeneration of skeletal, smooth and cardiac muscle. "ANGPT1 plays a key role in regulating the vascular endothelial barrier and its dysregulation has been implicated in chronic inflammation in Duchenne muscular dystrophy (DMD)." (PMID 41383381, 2025).
endometrioid endometrial carcinoma (1 paper, 2003). "We investigated the presence of transcripts for VEGF-A, VEGF-B, VEGF-C, VEGF-D, Angiopoietin-1 and Angiopoietin-2 in benign endometrium, atypical complex hyperplasia (ACH) and endometrioid endometrial carcinoma using in situ hybridisation." (PMID 12942123, 2003).
gastric ulcer (1 paper, 2021). An ulcerated lesion in the mucosal surface of the stomach. "Additionally, a local therapy with VEGF plus angiopoietin 1 cDNAs or with serum response factor (SRF) plasmid dramatically accelerates gastric ulcer healing and improves the quality of mucosal restoration within ulcer scars." (PMID 34440733, 2021).
gastritis (1 paper, 2023). Inflammation of the stomach. "Therefore, we used a mouse model of H. pylori-induced gastritis to explore the kinetics of the expression of Angpt1, Angpt2, Tnf-α and Vegf-A in vivo." (PMID 36874142, 2023).
glomerular disease (1 paper, 2020). "In physiology, Angpt1 is expressed by glomerular cells and pericytes, while Angpt2 expression is absent; increased levels of Angpt2 have been observed in glomerular diseases and appear to be correlated to adverse outcomes." (PMID 33067928, 2020).
hemorrhagic fever (1 paper, 2018). An infectious disease caused by certain viruses or bacteria that can damage the walls of tiny blood vessels, making them leak, and can hamper the blood's ability to clot and cause severe, life-threatening illness. "One of the groups scanned KFDV virus genome and predicted eight mature miRNAs that regulate two host target genes i.e., ANGPT1 (angiopoietin 1) and TFRC (transferrin receptor) which are involved in hemorrhagic fever and neurological manifestations." (PMID 29868505, 2018).
hemorrhagic stroke (1 paper, 2021). A stroke caused by a bleed on the brain. "Polymorphisms in the mice ortholog of ANGPT1 were reported as genome-wide significant hits in a study of mice using cerebral artery occlusion model, and human population studies have reported a few genetic variants of ANGPT1 associated with ischemic and hemorrhagic stroke." (PMID 35359917, 2021).
hypothyroidism (1 paper, 2011). Abnormally low levels of thyroid hormone. "Hypothyroidism significantly affected the expression of five genes: expression of Angiopoietin 1 (Angpt1) was downregulated and the expression or the remaining four genes was upregulated (p<0.05)." (PMID 21966411, 2011). "Notably, expression pattern of four out of five genes affected by hypothyroidism (Angpt1, CD55, Cited1, and Mdk) was reversed by T3 treatment of hypothyroid animals, (p<0.05)." (PMID 21966411, 2011).
inflammatory bowel disease (1 paper, 2018). A spectrum of small and large bowel inflammatory diseases of unknown etiology. "Furthermore, blood serum angiopoietin-1 levels are elevated in patients with UC and can be used as a factor for studying the progression of inflammatory bowel disease (IBD)." (PMID 29610929, 2018).
inner ear disorder (1 paper, 2024). A non-neoplastic or neoplastic disorder affecting the inner ear. "Pericyte-derived factors, such as angiopoietin-1 and PDGF-BB, are potential biomarkers for inner ear disorders." (PMID 39452111, 2024).
intracerebral hemorrhage (1 paper, 2024). A cerebrovascular disorder characterized by bleeding into one or both cerebral hemispheres including the basal ganglia and the cerebral cortex. "NSCs also produce blood–brain barrier stabilizing factors such as vascular endothelial growth factor (VEGF) and angiopoietin-1 (Ang1) that limit intracerebral hemorrhage and edema." (PMID 39200128, 2024).
ischemia reperfusion injury (1 paper, 2019). Adverse functional, metabolic, or structural changes in ischemic tissues resulting from the restoration of blood flow to the tissue (reperfusion), including swelling; hemorrhage; necrosis; and damage from free radicals. "Damage to the endothelium due to ischemia reperfusion injury (IRI) leads to a disruption of the microvasculature, which could be influenced by angiopoietin 1 via its effects on endothelium." (PMID 30760202, 2019).
keratitis (1 paper, 2024). A corneal disease that is characterized by inflammation of the cornea. "Topical miR-204-5p after LPS-induced keratitis in mice failed to suppress Vegfa, Angpt1, Il-1β, and Tnf-α or rescue Pax6 levels in contrast to in vitro results, although it significantly reduced the inflammatory infiltrate in the cornea." (PMID 39488562, 2024).
kidney injury (1 paper, 2025). Trauma to the kidney. "ANGPT1, as well as ANGPT1 mimetics and transgenic expression of Angpt1, have demonstrated beneficial effects in various preclinical models of kidney injury." (PMID 40952790, 2025).
Lyme neuroborreliosis (1 paper, 2023). "However, except for a transcriptomic study concerning its diagnostic role in Lyme neuroborreliosis, studies on ANGPT1 with regard to CNS bacterial infection are still lacking." (PMID 37409018, 2023).
mantle cell lymphoma (1 paper, 2023). Mantle cell lymphoma is a rare form of malignant non-Hodgkin lymphoma affecting B lymphocytes in the lymph nodes in a region called the ``mantle zone''. "In SOX11-positive mantle cell lymphoma, increased tumor angiogenesis and higher levels of pro-angiogenic factors, including angiopoietin-1 and -2 and fibroblast growth factor-1, were observed." (PMID 37391758, 2023).
mastocytoma (1 paper, 2021). A localized tumor composed of sheets of mast cells without atypia. "It has been demonstrated that ANGPT1 inhibits the in vitro activation of the mouse mastocytoma cell line P815 and experimental anaphylactic shock in mice." (PMID 33687603, 2021).